RGN (regucalcin)
Description:
Gluconolactonase with low activity towards other sugar lactones, including gulonolactone and galactonolactone. Can also hydrolyze diisopropyl phosphorofluoridate and phenylacetate (in vitro). Calcium-binding protein. Modulates Ca(2+) signaling, and Ca(2+)- dependent cellular processes and enzyme activities (By similarity).
Synonyms: RC; GNL; SMP30; HEL-S-41
Tractability: Small molecule: a structure with a bound ligand is known; it has a high-quality binding pocket. PROTAC: its protein half-life has been measured.
Gene: Protein-coding gene on chromosome X (47,078,190 to 47,094,419, forward strand). Ensembl gene ENSG00000130988.
Subcellular location: Cytoplasm
Subcellular location (Human Protein Atlas): Cytosol
Gene Ontology:
Molecular function: calcium ion binding; gluconolactonase activity; zinc ion binding; enzyme regulator activity
Biological process: intracellular calcium ion homeostasis; positive regulation of ATP-dependent activity; regulation of calcium-mediated signaling
Cellular component: cytoplasm; nucleus
Homologues: Orthologues: chimpanzee RGN (99% identical), macaque RGN (98% identical), dog RGN (91% identical), guinea pig RGN (91% identical), pig RGN (89% identical), rabbit RGN (89% identical), mouse Rgn (89% identical), rat Rgn (89% identical), zebrafish rgn (63% identical), Drosophila melanogaster smp-30 (35% identical), Drosophila melanogaster regucalcin (34% identical).
Diseases named in the same sentence as RGN in open-access papers:
RGN is named in the same sentence as 68 diseases in open-access papers, as found by Europe PMC text mining. Sharing a sentence is not in itself a finding about the gene and the disease. The quoted sentences say what the papers report.
hepatoma (10 papers, 2008 to 2023). "The role of endogenous regucalcin in cell regulation has been shown in regucalcin/pCXN2-transfected hepatoma H4-II-E cells that overexpress regucalcin stably." (PMID 23670020, 2013). "There is growing evidence that overexpression of endogenous regucalcin suppresses apoptosis in modeled liver (rat hepatoma H4-II-E) cells and normal rat kidney proximal epithelial NRK52E cells that are induced through various signaling factors." (PMID 23670020, 2013). "Overexpression of endogenous regucalcin was found to suppress apoptosis in modeled rat hepatoma cells and normal rat kidney proximal epithelial NRK52 cells induced by various signaling factors." (PMID 23670020, 2013). "Overexpressed regucalcin has been shown to suppress cell proliferation enhancement and apoptotic cell death mediated by various signaling stimuli in cloned normal rat kidney proximal tubular epithelial cells and cloned rat hepatoma cells in vitro." (PMID 38001749, 2023). "Moreover, overexpression of regucalcin has been shown to have a suppressive effect on TNF-α-induced apoptosis in human hepatoma HepG2 cells." (PMID 23670020, 2013). "Stable and high level expression of SMP30/regucalcin has been demonstrated in several eukaryotic cell lines that include human hepatocellular carcinoma Hep G2, Rat hepatoma H4-II E, mouse embryonic carcinoma PC19 and normal rat kidney proximal tubular epithelial NRK 52E." (PMID 21347421, 2011). "In this animal model, the study identified a decrease in regucalcin mRNA expression in rat hepatoma tissues compared to non-tumor liver tissues." (PMID 38001749, 2023).
prostate carcinoma (9 papers, 2014 to 2025). A carcinoma that arises from epithelial cells of the prostate gland. "It was noting that high RGN expression was closely associated with prolonged survival of patients with cancers including prostate cancer, lung adenocarcinoma and colorectal cancer." (PMID 37161020, 2023). "Prostate cancer patients with a higher regucalcin expression showed a longer recurrence-free and overall survival." (PMID 39858022, 2025). "Prostate cancer patients with higher levels of regucalcin showed a longer progression-free survival than those with a lower regucalcin gene expression." (PMID 39858022, 2025). "Prostate cancer patients with higher regucalcin expression had a prolonged progression-free survival compared to those with lower regucalcin gene expression." (PMID 38001749, 2023). "When there is a decrease in regucalcin in human prostate cells, it leads to increased prostate cancer metastasis." (PMID 38001749, 2023). "It has been suggested that RGN has a physiological function in the prostate, as the expression of this protein is down-regulated in prostate cancer tissues, and RGN immunoreactivity is correlated with the grade of adenocarcinoma cellular differentiation." (PMID 25415588, 2014). "In addition, knockdown of regucalcin in the LNCap human prostate cancer cells resulted in an increase in the growth of mice’s tibias." (PMID 39858022, 2025). "Decreased RGN expression was identified in prostate cancer (PCa)." (PMID 39682121, 2024). "Regucalcin (RGN) promotes prostate cancer dormancy by enhancing key hallmarks of tumor dormancy." (PMID 39682769, 2024). "Decreased RGN expression was identified in several cancers, including prostate cancer (PCa)." (PMID 39682121, 2024). "Notably, an overexpression of regucalcin was found to suppress the migration and invasion of bone metastatic human prostate cancer cells in vitro." (PMID 38001749, 2023). "Additionally, the translational study demonstrated that in vitro overexpression of regucalcin significantly decreased colony formation and cell growth in bone metastatic human prostate cancer PC-3 and DU-145 cells." (PMID 38001749, 2023). "Interestingly, the study found that knocking down regucalcin in LNCap cells, a human prostate cancer cell line, led to their increased growth in the tibia of mice." (PMID 38001749, 2023). "Regucalcin plays a role in the suppression of prostate cancer." (PMID 38001749, 2023). "Thus, the overexpression of regucalcin in prostate cancer cells prevented aberrant bone cell differentiation." (PMID 38001749, 2023). "In addition, miR-23c secreted from prostate cancer cells expressing regucalcin, a gene involved in tumor dormancy, was found to suppress the angiogenesis in human umbilical vein endothelial cells." (PMID 35406622, 2022). "Although it was shown that dihydrotestosterone (DHT) down-regulated SMP30/regucalcin mRNA expression in prostate cancer LNCaP cells, this inhibitory effect was abolished by flutamide, an AR antagonist, suggesting that down-regulation of SMP30/regucalcin expression by DHT is through AR modulation." (PMID 27553527, 2016). "Thus, overexpression of regucalcin may have a protective effect against age-related pathologies, such as prostate cancer." (PMID 38001749, 2023).
breast carcinoma (8 papers, 2011 to 2025). "This study provides valuable information to comprehend the expression of regucalcin in different stages of mammary carcinoma and indicates its usefulness as a pan-species diagnostic marker." (PMID 38001749, 2023). "Regucalcin expression was found to be downregulated in the patients with breast cancer, and patients with higher levels of regucalcin in the tumor tissue had a longer recurrence-free survival." (PMID 39858022, 2025). "It was found that regucalcin expression is down-regulated in breast cancer patients, and patients with higher regucalcin levels had longer relapse-free survival." (PMID 38001749, 2023). "Overexpression of RGN can suppress bone metastatic activity of MDA-MB-231 human breast cancer cells." (PMID 37161020, 2023). "The expression pattern of regucalcin was compared in human, canine, and feline mammary carcinomas." (PMID 38001749, 2023). "Furthermore, regucalcin transgenic rats demonstrated a lower incidence of carcinogen-induced mammary tumors through a reduction in cell cycle inhibitors and an increase in apoptosis inducers." (PMID 38001749, 2023). "Interestingly, in human breast cancer MCF-7 cells, 17β-oestradiol’s actions in regulating RGN expression levels were suggested to be mediated by the membrane-bound G-protein-coupled oestrogen receptor (GPER)." (PMID 39682121, 2024).
diabetic nephropathy (5 papers, 2016 to 2026). "In vivo RGN knockout (KO) mouse studies revealed that RGN is related to the pathogenesis of diabetic nephropathy, nonalcoholic fatty liver disease, and hepatic steatosis." (PMID 34709731, 2022). "Diabetic nephropathy rats were shown to exhibit downregulated expression of RGN expression in kidney tissue and decreased amounts of RGN‐present exosomes in urine." (PMID 32783343, 2020). "Studies on in vivo RGN KO mice also revealed that RGN is related to the pathogenesis of diabetic nephropathy, nonalcoholic fatty liver disease, and hepatic steatosis." (PMID 32783343, 2020). "Decreased levels of miR-30b-5p, S100A8, S100A9 and regucalcin have also been described in diabetic nephropathy." (PMID 32849923, 2020). "Very recent study on diabetic nephropathy novel biomarkers revealed that exosomal regucalcin was underexpressed in renal disease patients." (PMID 28105442, 2016).
hyperlipidemia (5 papers, 2011 to 2021). "Retinal dehydrogenase 1, retinol-binding protein 1, and regucalcin are implicated in cholesterol and fat metabolism as well as in hyperlipidemia and diabetes." (PMID 30038271, 2018). "RGN overexpression was shown to induce hepatic insulin resistance and hyperlipidemia in rats." (PMID 34063343, 2021). "Regucalcin transgenic rats have been shown to experience hyperlipidemia with increasing age." (PMID 23724019, 2013).
Obesity (4 papers, 2013 to 2021). Accumulation of substantial excess body fat. "Higher expression of Regucalcin has been liked to adipogenesis in adipocytes, and also alterations in lipid and glucose metabolism in vivo, which are predisposing factors to obesity and diabetes." (PMID 30261666, 2018).
pancreatic cancer (4 papers, 2018 to 2025). "The survival of pancreatic cancer patients associated with an increase in regucalcin gene expression was prolonged." (PMID 39858022, 2025). "The function of regucalcin in human pancreatic cancer has been clarified through assessment of its expression levels in both normal pancreatic tissue and pancreatic ductal adenocarcinoma (PDA) among human subjects." (PMID 38001749, 2023). "Overexpression of Regucalcin has been demonstrated to suppress proliferation, cell death, and migration in an in vitro model of pancreatic cancer in a previous study." (PMID 33194391, 2020). "Regucalcin is shown to be a tumor suppressor in human pancreatic cancer." (PMID 39858022, 2025). "The survival of pancreatic cancer patients with increased regucalcin gene expression was extended." (PMID 38001749, 2023).
chronic hepatitis (3 papers, 2019 to 2023). An active inflammatory process affecting the liver for more than six months. "The rate of positivity for anti-regucalcin antibodies in HCC patients was higher than that in the chronic hepatitis group and the liver cirrhosis group." (PMID 38001749, 2023). "In addition, the regucalcin and anti-regucalcin antibody levels in the serum of 143 patients with HCC were compared to those in serum samples from 137 patients with chronic hepatitis, 51 individuals with liver cirrhosis, and 165 healthy control participants." (PMID 38001749, 2023).
heart failure (3 papers, 2013 to 2022). Inability of the heart to pump blood at an adequate rate to meet tissue metabolic requirements. "The aim of this review was to discuss the regulatory role of regucalcin in heart Ca2+ signaling, with insight into cardiac failure." (PMID 24748964, 2014). "Regucalcin may play a physiological role by exerting protective effects against heart failure, through the activation of SOD or the suppression of NO overproduction in heart cells." (PMID 24748964, 2014). "Regucalcin (RGN), which has been shown to increase rat heart sarcoplasmic reticulum Ca2+-ATPase activity and ATP‐dependent Ca2+ uptake, is a key molecule in heart muscle cell regulation through Ca2+ signalling, and has been suggested to play a pathophysiological role in heart failure." (PMID 35428319, 2022). "Regucalcin may also play a pathophysiological role in heart failure." (PMID 24748964, 2014).
liver cancer (3 papers, 2022 to 2025). An epithelial or non-epithelial malignant neoplasm that arises from the liver. "In modeled human liver cancer HepG2 cells, extracellular regucalcin was found to have suppressive effects on cell growth in vitro." (PMID 38001749, 2023). "Regucalcin is highly expressed in both animal and human liver and is suppressed in liver cancer of humans." (PMID 38001749, 2023). "Dendritic cells (DC) pulsed with recombinant regucalcin were shown to induce cytotoxic T lymphocytes (CTLs) against liver cancer cells in vitro." (PMID 38001749, 2023). "Translational studies have demonstrated that the overexpression of regucalcin inhibits the proliferation, cell death, and migration of human liver cancer HepG2 cells in vitro." (PMID 38001749, 2023). "Regucalcin expression is downregulated in human liver cancer." (PMID 39858022, 2025). "Regucalcin mRNA is expressed in liver cancer cells at lower levels." (PMID 39858022, 2025). "The expressions of regucalcin are decreased in liver cancer cells compared to normal livers." (PMID 38001749, 2023).
nonalcoholic fatty liver disease (3 papers, 2020 to 2022). "The use of RGN−/− mice unveils the potential roles of RGN in Glc metabolism and non-alcoholic fatty liver diseases, as was recently overviewed." (PMID 36234722, 2022).
atherosclerosis (2 papers, 2021 to 2024). A disease characterized by the build-up of fatty material and calcium deposition in the arterial wall resulting in partial or complete occlusion of the arterial lumen. "Accordingly, we consider that low expression of YTHDC1 leads to elevated RGN expression by promoting macrophage inflammation, which increases apoptosis in vascular smooth muscle cells and ultimately exacerbates atherosclerosis." (PMID 38168909, 2024). "Furthermore, the sustained release of inflammatory factors may increase the expression of the aging-related gene RGN in vascular smooth muscle cells, further exacerbating the progression of atherosclerosis." (PMID 38168909, 2024).
Insulin resistance (2 papers, 2018 to 2021). Increased resistance towards insulin, that is, diminished effectiveness of insulin in reducing blood glucose levels. "As well as other proteins, such as 60 kDa heat shock protein, peroxiredoxin-1, pyruvate carboxylase and regucalcin; they have been found increased in different models of insulin resistance." (PMID 29857581, 2018).
lung adenocarcinoma (2 papers, 2023 to 2025). A carcinoma that arises from the lung and is characterized by the presence of malignant glandular epithelial cells. "The GEO database of 204 patients with lung adenocarcinoma showed that regucalcin was decreased in the patients with lung cancer, and a higher regucalcin gene expression led to prolonged survival in lung cancer patients." (PMID 39858022, 2025).
lung carcinoma (2 papers, 2023 to 2025). "The results revealed that regucalcin expression was downregulated in lung cancer patients." (PMID 38001749, 2023). "Notably, the decreased expression of regucalcin contributes to the growth of human lung cancer." (PMID 38001749, 2023). "Moreover, higher regucalcin gene expression led to prolonged survival in lung cancer patients." (PMID 38001749, 2023).
male infertility (2 papers, 2018 to 2024). The inability of the male to effect fertilization of an ovum after a specified period of unprotected intercourse. "Moreover, RGN is also a calcium (Ca2+)-binding protein, playing an important role in regulating Ca2+ homeostasis, and the Ca2+ homeostasis disruption may cause reversible male infertility." (PMID 38529408, 2024). "Overall, these discoveries extended the array of RGN roles supporting a successful spermatogenesis and highlighted for the plasticity of SCs metabolism, which could be of uttermost importance in the context of male infertility." (PMID 29985416, 2018).
melanoma (2 papers, 2023 to 2025). A malignant, usually aggressive tumor composed of atypical, neoplastic melanocytes. "An affinity proteomics analysis of 149 serum samples from melanoma patients showed lower serum regucalcin and syntaxin 7 levels as compared with these levels in those with no recurrence." (PMID 39858022, 2025). "Regucalcin shows potential as a new biomarker for human melanoma." (PMID 38001749, 2023). "Regucalcin may be a significant biomarker in human melanoma." (PMID 38001749, 2023).
non-small cell lung carcinoma (2 papers, 2019 to 2022). A group of at least three distinct histological types of lung cancer, including non-small cell squamous cell carcinoma, adenocarcinoma, and large cell carcinoma. "An analysis of RGN expression by means of immunohistochemistry suggests that a low expression of RGN is associated with the development of non-small cell lung cancer." (PMID 36234722, 2022).
age (1 paper, 2018). A temporal measurement of the time period elapsed since an identifiable point in the life cycle of an organism. "Because RGN is a reported functional inhibitor of Ca2+/calmodulin‐dependent protein kinase 32 and calpains 33, 34, dysregulation of neuronal Ca2+ homeostasis during age‐related cognitive declines and neurodegenerative disease may be associated with decreased RGN expression." (PMID 29511612, 2018).
cervical adenocarcinoma (1 paper, 2024). An adenocarcinoma arising from the cervical epithelium. "In a study with human cervical adenocarcinoma HeLa cells, it was reported that RGN knockdown increased migration, invasion and metastisation through the upregulation of N-cadherin and vimentin." (PMID 39682121, 2024).
cholangiocellular carcinomas (1 paper, 2020). "A study on zebrafish demonstrated that RGN was downregulated in hepatocellular and cholangiocellular carcinomas and played a significant role in cell proliferation and tumorigenesis." (PMID 32742447, 2020).
colorectal cancer (1 paper, 2023). A primary or metastatic malignant neoplasm that affects the colon or rectum. "Prolonged survival among colorectal cancer patients is significantly linked with elevated regucalcin gene expression in their tumor tissue." (PMID 38001749, 2023). "In vitro translational findings reveal how overexpressed regucalcin can lead to the suppression of colony formation and proliferation of human colorectal-cancer-derived RKO cells." (PMID 38001749, 2023). "Regucalcin expression was reduced in colorectal cancer patients." (PMID 38001749, 2023).
lipid metabolism disorders (1 paper, 2014). "We are reporting for the first time that n-3 PUFA down-regulates the expression of regucalcin, a potent player in lipid metabolism disorders." (PMID 24438320, 2014).
lung squamous cell carcinoma (1 paper, 2023). "However, the role of RGN in the tumor immunological microenvironment in lung squamous cell carcinoma (LUSC) remains unclear." (PMID 37161020, 2023).
renal carcinoma (1 paper, 2024). A carcinoma arising from the epithelium of the renal parenchyma or the renal pelvis. "The downregulated expression of RGN was also associated with the onset of lung, pancreatic, colorectal, hepatocellular and renal carcinomas." (PMID 39682121, 2024).
renal failure (1 paper, 2023). "Moreover, it emphasized that suppressed regucalcin gene expression might contribute to the development of renal failure." (PMID 37928042, 2023).